IL21 (interleukin 21)
Diseases named in the same sentence as IL21 in open-access papers (continued):
Sharing a sentence is not in itself a finding about the gene and the disease.
infection (continued). "The reasons for these differential requirements for IL-21 in the different infections/immunizations are not known." (PMID 25763578, 2015). "The slightly higher numbers of Tfh cells in Il21-/- and Il21r-/- at day 120 post-infection compared with those in WT C57BL/6 mice might have been a consequence of the on-going infection promoting continued T cell activation." (PMID 25763578, 2015). "Contrary to its importance in generating B cell responses after immunization, IL-21 seems not to be necessary for all aspects of T-cell-dependent B cell responses in different infection models." (PMID 25763578, 2015). "Moreover there is a group of molecules, including LTA, LTB, IL21, IFNAR2, CXCR3, IL17F and CD40LG, whose expression increased over the course of USA300 infection." (PMID 25719526, 2015). "With the progression of the infection a more equilibrated immunological balance is observed, with 6 genes showing significant transcription up-regulation: IFN-γ, IL-5, TNF-α, TGF-βR1, IL-21 and IL-23 and 4 extra genes showing significant down-regulation: DEFB1, CD163, IL-13 and IL-18." (PMID 26589145, 2015). "In conclusion, our data indicates that the defect in establishment of latency in the absence of IL-21 signaling occurs at the centrocyte stage of infection." (PMID 25875847, 2015). "In some individuals, particularly at day >180 post-infection, IL-21 mRNA was also detected in non-Tfh cell subset." (PMID 26640894, 2015). "IL-21 has been shown to be important for development of B-cell responses after immunization; however, a direct requirement for IL-21 in the control of infection via B-cell dependent mechanisms has never been demonstrated." (PMID 25763578, 2015). "Upregulation of IL21 has been reported in LCMV model of HF and has been linked to the clearance of infection but had not previously been noted in LASV infection." (PMID 23638192, 2013). "Similar to results observed with Il21r−/− mice, intraperitoneal infection of Il21−/− mice with cysts from the ME49 strain of T. gondii did not result in increased susceptibility to acute or chronic disease over the time course examined." (PMID 23667536, 2013). "Therefore, Il21−/− mice were challenged with T. gondii to determine whether IL-21 impacts the parasite-specific CD8+ T cell response, its contribution to thymus-dependent antibody production after infection, and balance between protective and pathogenic responses." (PMID 23667536, 2013). "The enhanced expression of IL-21 in vivo, in the GALT early in infection might serve as a transient immune enhancing mechanism to restore the massively depleted CD4+ T and Th17 cell populations." (PMID 22511950, 2012). "During the effector phase of the CD8 T cell response, at day 9 following infection, LCMV GP33-specific CD8 T cells from all of the cohorts analyzed produced IFN-γ in response to a brief (5.5 hr) exposure to IL-12+IL-18 and IL-12+IL-18+IL-21." (PMID 21980291, 2011). "In order to examine the impact of IL-21 on the establishment of KSHV infection, we performed Mock infection or KSHV infection in 13 unique tonsil samples and left the cultures untreated or supplemented the resulting cultures with varying concentrations of recombinant human IL-21(IL-21)." (PMID 36569889, 2022). "IL-21 can also promote B cell responses, the development of Th17 CD4+ T cells, and Tfh CD4+ T cells, which may assist in the resolution of inflammation and the infection." (PMID 34696381, 2021). "Moreover, after removing individuals with genital inflammation from the analysis, 11 of the biomarkers remained significantly higher in the pre-infection group compared to the uninfected group (Fractalkine, GMCSF, ITAC, IL-1ß, IL-6, IL-7, IL-8, IL-21, MIP-1α, MIP-3α, and TNFα)." (PMID 33731158, 2021). "In our experiment, cytokine values, especially IFN-γ, IL-10, and IL-21, were not particularly high, which may be related to the low number of cercariae infection." (PMID 33330140, 2020).
infection (continued). "Interestingly, the colonic intestinal epithelial cells (IECs) expressed neither detectable transcripts for IL-21 nor mRNA for IL-21R following infection." (PMID 30818341, 2019). "Moreover, using Il21-mCherry reporter transgenic (TG) mice, we found that lung CD4+ T cells had low basal mCherry expression, but the percentage and total number of Il21-mCherry expressing cells increased after infection with MRSA." (PMID 30969166, 2019). "However, the regulation of the CXCR5+IL-21+IFN-γ+ subset was independent of Bcl6 during infection of P. chabaudi in the mouse." (PMID 31867283, 2019). "Flow cytometry analysis revealed that, although conventional CD4+ T cells gradually express CXCR5, PD-1, Bcl6, and SLAM and produce high levels of IL-21 after infection, TCRβ+CD1d-tetramer+ NKT cells do not upregulate Bcl6, CXCR5, or PD-1 and express moderate levels of SLAM and IL-21." (PMID 29249358, 2018). "Moreover, IL-21 acting on B cells and CD4+ T cells is critical for generating long-lived plasma cells after infection with an acute strain of LCMV, vesicular stomatitis virus, and influenza virus, highlighting the importance of IL-21 in humoral immunity during viral infection." (PMID 26966515, 2016). "There is a significant reduction in the frequency of splenocytes capable of reactivation at later time points, but the defect is minor at day 14 post-infection, suggesting that IL-21 signaling is not required for virus production during initial seeding of the spleen." (PMID 25875847, 2015). "At no point during the infection was IL-21 detectable in NK cells, CD19+ cells or CD3–NK1.1– cells." (PMID 25763578, 2015). "Moreover, IL-21 signaling is required to activate P. chabaudi-specific IgG MBC responses, and to develop immunity to homologous secondary P. chabaudi and P. yoelii 17X(NL) infections." (PMID 25763578, 2015). "A recent study in mice reported that memory TFH cells have reduced mRNA expression of TFH markers such as Bcl6, IL-21, ICOS and PD-1 compared to the effector TFH population, indicating the expression of these molecules may change depending on the phase of infection." (PMID 24497824, 2014). "Therefore, during chronic LCMV-DOC infection, the inhibition of virus-induced Treg cell expansion is a distinct function of IL-21, which is not accompanied by elevated IL-17 production of CD4+ T cells." (PMID 23696736, 2013). "Reduced plasma levels of IL-21 have been found in HIV-infected individuals, and we recently showed that pathogenic SIV-infection of RMs, but not nonpathogenic SIV infection of sooty mangabeys is associated with a significant loss of IL-21-producing CD4+ T cells." (PMID 23853592, 2013). "Moreover, the baseline frequency of IL-21 positive CD8+ central memory T cells was also significantly correlated with KSHV infection of plasma cells at 3dpi (r=0.76, p=0.03; σ=0.76, p=0.04) and negatively correlated with infection of naïve B cells (r=-0.72, p=0.04)." (PMID 36569889, 2022). "Interestingly, Il21−/− mice showed no immune-mediated pathology during the acute phase of infection and IgG production was impaired in these mice as compared with wild-type controls and the impairment in IgG production in Il21−/− mice correlated with diminished numbers of GC B cells." (PMID 31867283, 2019). "As IL-21 signaling is required to control the chronic phase of P. chabaudi infection and Tfh cells are an important source of IL-21, we reasoned that the lack of IL-21 signaling would impair the development of protective B cell responses and consequently prevent the resolution of the infection." (PMID 25763578, 2015). "Finally, it is interesting to note that STAT3-dependent cytokines, such as IL-6, IL-10, and IL-21, as well as MyD88-dependent IL-1 have been suggested to play a role in memory CD8+ T cell differentiation and functional maturation following immunization and infection." (PMID 24842874, 2014).
infection (continued). "Blimp-1 plays a larger role in longer infection, as only untreated infected Blimp-1 TKO (NTx), but not treated, had fewer IFN-γ+IL-21- with a concomitant increase in hybrid IFN-γ+IL-21+, supporting its role in IL-10 expression." (PMID 32634740, 2020). "During murine CMV (MCMV) infection, CD4+ Tcells maintain inflationary virus-specific CD8+ T-cell responses via IL-2 but not IL-21." (PMID 30279090, 2018). "While IL-21 and CXCR5, widely considered Tfh-related molecules, are both predominantly expressed by IFN-γ+ cells in this infection, this population is not regulated by Bcl6." (PMID 26646149, 2015). "To explore the significance of IL-21-mediated viral inhibition, we assessed CD4 T-cell depletion in HLACs in the presence and absence of IL-21 6 days post infection." (PMID 26108174, 2015). "The lack of IL-21 signaling in B cells impacts MHV68 infection at multiple levels, resulting in significantly reduced infection." (PMID 25875847, 2015). "In conclusion, induction of a balanced Th1/Th17 response and production of key effector cytokines, such as IFNG, IL2, IL17, IL21, IL22 and IL23A was observed in animals that controlled infection, regardless of previous BCG-vaccination." (PMID 24505407, 2014). "IL-21 did not change the frequencies of CD8+tet+ cells, which increased similarly in both groups following infection (data not shown)." (PMID 23853592, 2013). "In the absence of IL-21, CD8+ T cells cannot control the infection and are deleted." (PMID 34696381, 2021). "Other immunoregulatory markers such as IL-21, FoxP3 and TGF-β showed no significant expression variations between vaccinated and infected control group (group C) although a tendency of being dysregulated during infection was detected." (PMID 32517744, 2020). "Collectively, these findings suggested that IFN-γ is the predominant interferon produced in the colon in response to C. rodentium and that the lack of an intact IL-21/IL-21R signaling axis does not negatively affect the IFN-γ expression and production in response to infection in Il21r-/- mice." (PMID 30818341, 2019). "Similar to Tfh responses during primary infection, Tfh responses during second P. chabaudi infection and IFN-γ responses of CD4+ T cells during primary and second P. chabaudi infection were not altered by the absence of IL-21 signaling." (PMID 25763578, 2015). "Furthermore, no immunopathology was apparent in Il21−/− mice over the course of the infection, nor was there a defect in development of IL-10+ CD4+ T cells in chronically infected Il-21−/− mice." (PMID 23667536, 2013). "In order to examine this hypothesis, we analyzed IL-21R expression on B cell subsets at 3 dpi in our culture system with or without IL-21 supplementation to determine whether KSHV and/or IL-21 can modulate the response to IL-21 during infection by modifying expression of IL-21R." (PMID 36569889, 2022). "However, unlike IL-21, CD4 T cell-derived IFNγ may act by primarily promoting CD8 T cell entry into the site of infection." (PMID 31514273, 2019). "Interestingly, treatment of WT mice with IL-21, as opposed to PBS, prior to intratracheal infection with MRSA resulted in a modest but significant increase in pulmonary clearance of bacteria at both 7 and 24 hr (see summary of 6 independent experiments at 7 hr)." (PMID 30969166, 2019).
cancer (127 papers, 2006 to 2026). A tumor composed of atypical neoplastic, often pleomorphic cells that invade other tissues. "Although IL‐21 primarily signals via a STAT3, NF‐κB inhibition caused a lower proliferation in the presence of IL‐21, indicative of the complex interplay between these two pathways on NK cell proliferation, which has previously been observed in cancer." (PMID 39865344, 2025). "A highly attenuated IL-21 mutein variant (R9E:R76A) fused to a PD-1 antibody provides protection in a humanized mouse model of cancer that is refractory to anti-PD-1 monotherapy." (PMID 32457754, 2020). "IL-21/IL-21R signaling plays critical role in immune responses and has been implicated in the regulation of inflammation in various acute and chronic inflammatory diseases, such as cancer." (PMID 38720319, 2024). "IL-21, an immunomodulatory cytokine with potential in cancer therapy, has unexplored synergy with radiotherapy." (PMID 41505202, 2026). "Cytokines from the common gamma chain receptor family, such as IL-15, IL-21 and IL-7, show promise for cancer immunotherapy and have been incorporated individually into the immunocytokine approach." (PMID 40370435, 2025). "The administration of recombinant IL-21 has been shown to rejuvenate exhausted NK cells in both animal models and human cancer patients." (PMID 40176196, 2025). "The data showed that IL-21 expression was positively correlated with the infiltrations of NK cells and T cells in a number of cancers." (PMID 38263004, 2024). "This review focuses on ICKs designed with the most impactful cytokines in the cancer field: IL-2, TNFα, IL-10, IL-12, IL-15, IL-21, IFNγ, GM-CSF, and IFNα." (PMID 39204319, 2024). "In this regard, several studies have investigated the potential of harnessing T cell based ACT involving IL-21 to improve cancer treatment and we have highlighted some of them below." (PMID 38638431, 2024). "Oncolytic viruses armed with interleukin-21 demonstrated superior antitumor efficacy in several cancer models." (PMID 38638431, 2024). "In other cancers, IL-21 blockade was able to drastically reduce B cell activation induced by co-administration of anti-PD-1 and anti-CTLA-4 therapy, highlighting the importance of Tfh cell-secreted effector molecules in cancer immunotherapy." (PMID 38649788, 2024). "In the present review, we will outline the recent progress in IL-21 research, highlighting the potential of IL-21 based therapy as single agent or in combination with other drugs to enhance cancer treatment efficiency." (PMID 38638431, 2024). "The combination of these three therapies—MWA, IL-21, and anti-PD-1 monoclonal antibodies (mAbs)—has yet to be explored in the context of cancer treatment." (PMID 38833177, 2024). "Many cytokines, including GM-CSF, IL-7, IL-12, IL-15, IL-18, and IL-21, have entered clinical studies for people with advanced cancer." (PMID 38360737, 2024). "In the TME of different cancers, Tfh cells have been identified as the main source of IL-21, another B cell-supporting cytokine." (PMID 38649788, 2024). "Many cytokines, including GM-CSF, IL-7, IL-12, IL-15, IL-18, and IL-21, have entered clinical trials for people with advanced cancer, while the FDA has approved interferon-alpha and IL-2." (PMID 38360737, 2024). "IL-21 is a key γc cytokine with a broad range of activities on B and T cells, but its pleiotropy hinders its clinical use, for example in cancer, by virtue of its activity on CD8+ T cells or as a vaccine adjuvant, by virtue of its activity on Tfh and B cells." (PMID 37339051, 2023). "The role of Tfh-derived IL21 in ICI cancer immunotherapy needs to be established using a relevant mouse model." (PMID 37546701, 2023). "Among them, we selected Il-21, Cxcl13, Cdk6, Cdk1, and Cxcr7, all cytokine, cell cycle, or cancer-related genes." (PMID 37304286, 2023).
cancer (continued). "It has been shown that priming of T cells with IL-21 and IL-15 before using in cancer T-cell therapy prolongs the life of these therapeutic T cells in a cancer mouse model." (PMID 37746258, 2023). "By contrast, IL-21 is potent, particularly in combination with cancer-targeting monoclonal antibodies (mAbs)." (PMID 35606854, 2022). "Another study illustrated that nivolumab enhances the antitumor effect of recombinant IL-21 in several cancer mouse models." (PMID 35402219, 2022). "There are two general areas where the positive effects of IL-21 are important: cancer immunotherapy and the development of memory responses to various viral pathogens." (PMID 35777300, 2022). "Both IL-15 and IL-21 are members of the IL-2 family and have been investigated to evaluate their therapeutic potentials for cancer treatment." (PMID 35795050, 2022). "This study reveals the mechanisms of IL21/PD-1 cooperation and shed light on rational design of novel combination cancer immunotherapy." (PMID 34869384, 2021). "During the last two decades, several attempts to enhance NK cell functions as a therapy for the treatment of AML or other cancers have been tested including the stimulation in vitro or in vivo by γc cytokines (IL-2, IL-15, IL-21, etc.)." (PMID 34975835, 2021). "The additive effect provided by combination therapy shows that IL21 as a cancer immunotherapeutic is limited by the immune checkpoint molecule PD-1." (PMID 34869384, 2021). "Interleukin 21 (IL21) as a single agent has been evaluated for cancer treatment with good clinical efficacy." (PMID 34869384, 2021). "The simulation shows that a cell carrying a genetic lesion has the risk to transform into a cancer cell, in this case, in a specific environment with active BCR and IL21/4." (PMID 34829885, 2021). "For instance, in vivo activation of NK cells using cytokine treatments (e.g., IL2, IL12, IL15, IL18 and IL21) has been investigated in several types of mouse cancer models and human cancers." (PMID 35008348, 2021). "As the PD-L1/PD-1 pathway has been recognized as a molecular checkpoint in immune evasion in various cancers, we next examined the effect of IL-21 on Treg generation from CD4+ T cells in the presence of PD-L1." (PMID 34026621, 2021). "Recent studies indicate that interleukin 21 (IL-21) and interleukin 22 (IL-22) play an important role in the pathogenesis of cancer and cancer therapy." (PMID 34300224, 2021). "Recombinant free IL-21 provides modest protection in various preclinical cancer models that is further amplified upon combination with other immune therapies." (PMID 32457754, 2020). "Whilst the effect of IL21 therapy on the remaining immune system cell populations of cancer patients remains unexplored." (PMID 32582698, 2020). "Interleukin-2 (200 IU/mL) and IL-21 (20 ng/mL) were tested, as these cytokines are known to bear the highest potential for the generation of anti-cancer immune effector cells." (PMID 31336622, 2019). "Another cytokine that is CD4 T cell-specific and important in cancer setting is Interleukin 21 (IL-21)." (PMID 31186477, 2019). "Preclinical experiments with several murine cancer models showed very promising antitumor effects of granulocyte–macrophage colony-stimulating factor (GM-CSF), IL-2, IL-12, IL-15, and IL-21." (PMID 31083515, 2019). "Previous studies have established the efficacy of irradiated cancer cells overexpressing GM-CSF or IL-21 as a vaccine." (PMID 31467912, 2019). "Collectively, these trials indicate the benefit of IL-21 as a monotherapy and warrant the investigation combining IL-21 with other agents for cancer therapy." (PMID 30842774, 2019). "In agreement with the existing evidence, treating whole blood of patients with cancer with IL-2, IL-15 and IL-21 markedly improved the antigen-specific IFNγ response regardless of existing immunosuppression, thereby suggesting clinical applicability." (PMID 29970101, 2018).